TG (thyroglobulin)
Diseases named in the same sentence as TG in open-access papers (continued):
Sharing a sentence is not in itself a finding about the gene and the disease.
vitiligo (16 papers, 2015 to 2024). Generalized well circumscribed patches of leukoderma that are generally distributed over symmetric body locations and is due to autoimmune destruction of melanocytes. "The presence of anti-TPO antibodies was significantly associated with a long duration of vitiligo and a positive family history of vitiligo, and anti-thyroglobulin antibodies were significantly associated with the female gender." (PMID 36556267, 2022). "Among 325 vitiligo patients identified, anti-thyroid peroxidase and anti-thyroglobulin were positive in 90 (27.7%) and 63 patients (19.4%), respectively." (PMID 29362715, 2017). "In vitiligo patients, 9 (8.3%) had elevated anti-TG levels and 16 (14.8%) had elevated anti-TPO, and in 17 patients (15.7%) TSH levels were elevated and 3 (2.8%) patients had elevated fT4 levels and 5 (4.6%) had elevated fT3 levels." (PMID 26355833, 2015). "We showed that THAbs have a surprisingly elevated prevalence in vitiligo, higher than in other disease investigated so far, and significantly correlate with active vitiligo, leukotrichia, disease duration, and thyroglobulin antibodies positivity." (PMID 25838868, 2015). "Vitiligo was the most frequent coexisting disease—every case of vitiligo was associated with the presence of thyroid autoantibodies, and ~7.5% of girls with positive anti-TPO or/and anti-TG had vitiligo." (PMID 31417494, 2019). "The genetic susceptibility to vitiligo has been studied extensively, identifying several gene loci associated with autoimmune-based thyroid dysfunction: these include genes encoding protein tyrosine phosphatase non-receptor type 22 (or PTPN22), tyrosinase, thyroglobulin (TG), and TSH-R." (PMID 39767917, 2024). "It is not apparent what role thyroglobulin might play in vitiligo pathogenesis, suggesting association of vitiligo with the TG/SLA locus may derive from SLA, rather than TG." (PMID 26870082, 2016). "Candidate gene association studies and genome-wide linkage analysis identified nine loci involved in both vitiligo and autoimmune thyroid disease, including genes coding for tyrosine (TYR), thyroglobulin (Tg), and thyroid-stimulating hormone receptor (TSHR)." (PMID 35204408, 2022). "Anti-thyroid peroxidase antibodies were found in two (no hormonal imbalances; anti-thyroglobulin antibodies negative in all children), hypogammaglobulinemia in three, and vitiligo in one child." (PMID 37131308, 2023). "Patients were investigated for demographics, vitiligo characteristics, and laboratory tests, including zinc, Vit-D, T3 (triiodothyronine), T4 (thyroxine), thyroid-stimulating hormone (TSH), thyroid peroxidase antibody (TPOAb), and thyroglobulin antibody (TGAb)." (PMID 36569724, 2022).
anemia (14 papers, 2016 to 2025). A reduction in the number of red blood cells, the amount of hemoglobin, and/or the volume of packed red blood cells. "Frailty was associated with elevated thyroglobulin (p = 0.029), whereas anemia was associated with lower thyroglobulin (p = 0.016)." (PMID 27455319, 2016). "It would be of interest to further investigate the relation between anemia and serum thyroglobulin, given anemia increases with age, and might be an important confounder when assessing iodine status using thyroglobulin concentration in older adults." (PMID 27455319, 2016). "We did not detect any effect of systemic inflammatory biomarkers (e.g., hs-CRP, interleukin 6, and alpha-1-acid glycoprotein (data not shown)) that are often associated with lower serum proteins, including hemoglobin, on the relation between serum thyroglobulin concentration and anemia." (PMID 27455319, 2016). "According to the increase of thyroglobulin antibody after the first RAI treatment (thyroglobulin antibody: 13.79IU/ml), and the indication of several cervical lymph nodes, combined with the fact that nuclear medicine doctors did not notice the patient ‘s anemia status." (PMID 40630205, 2025).
celiac disease (14 papers, 2012 to 2025). An autoimmune genetic disorder with an unknown pattern of inheritance that primarily affects the digestive tract. "The study also showed a very strong correlation between antibodies against tissue transglutaminase appearing in the blood of patients with celiac disease and antibodies against thyroglobulin (r = 0.781 and p = 0.007)." (PMID 41294849, 2025). "It has previously been reported that human TG-2 and TG-2 from guinea pig liverare highly comparable in detection of human anti-TG2 autoantibodies when used in a diagnostic test for coeliac disease." (PMID 22507564, 2012). "Apart from T1Ab negativation, some children, all younger than 3 years of age, also negativized anti-TG, anti-TPO and anti-TTG IgA, implying that reversal of seroconversion in younger children possibly provides additional protection from Hashimoto’s and celiac disease." (PMID 37238410, 2023). "Accordingly, the next stage of treatment in patients with Hashimoto’s should include screening for thyroglobulin antibodies (anti-TG), anti-deamidated gliadin peptid (anti-DPG), endomysial antibodies (EMA), and anti-gliadin antibodies (AGA) to exclude subclinical celiac disease and NCGS." (PMID 35565695, 2022).
Cognitive impairment (14 papers, 2018 to 2025). Abnormal cognition is characterized by deficits in thinking, reasoning, or remembering. "The results demonstrated a strong direct correlation between cognitive impairment as measured by the MMSE test and the levels of TSH, fT4, anti-TG and anti-TPO antibodies, 25-OH vitamin D, and brain-derived neurotrophic factor (BDNF)." (PMID 39768799, 2024).
Hyperglycemia (14 papers, 2015 to 2025). An increased concentration of glucose in the blood. "As regards to thyroid hormones, only free T3 showed lower levels in subjects with hyperglycemia, high TG, and elevated WC." (PMID 30151097, 2018).
thyroid storm (14 papers, 2015 to 2026). "Eight days later, he presented with signs of thyroid storms, such as tachycardia, hyperthermia, sweating and irritation, and his thyroid function tests revealed high levels of TPO-Ab, TR-Ab, TG-Ab, FT3 and FT4." (PMID 35794521, 2022).
anaplastic thyroid carcinomas (11 papers, 2007 to 2026). "We considered the possibility of undifferentiated thyroid carcinoma and the production of thyroglobulin." (PMID 24407283, 2014). "Because only 20% to 30% of anaplastic thyroid carcinomas are positive for thyroid markers such as thyroglobulin, it is important to be aware of any previous malignancies so appropriate marker staining can be done." (PMID 18157914, 2007). "In anaplastic thyroid carcinoma, thyroglobulin levels are generally low or undetectable." (PMID 39744583, 2025). "With that being said, primary lung adenocarcinomas are also positive for TTF-1, which creates diagnostic confusion (if thyroglobulin is negative), when a poorly differentiated or anaplastic thyroid carcinoma is being differentiated from a primary lung adenocarcinoma." (PMID 27774331, 2016). "Immunohistochemical analysis for thyroglobulin (TG), Galectin-3, CK19, CyclinD1, TTF-1, and EMA was performed to rule out the possibility of spindle cell variants of undifferentiated carcinoma of the thyroid." (PMID 32430041, 2020). "It is important to highlight that anaplastic thyroid carcinomas also do not always react to thyroglobulin and 20-30% of the cases are negative on thyroid-specific immunohistochemistry." (PMID 28225857, 2017). "On the other hand, undifferentiated thyroid carcinomas, such as anaplastic carcinoma, are by definition thyroglobulin negative and almost always TTF1 negative." (PMID 27213120, 2016). "In most cases of anaplastic thyroid carcinoma, thyroglobulin will be negative, while 15% will show Napsin-A positivity." (PMID 27774331, 2016). "It is important to note however that the majority of anaplastic thyroid carcinomas also do not have a positive reaction to thyroglobulin." (PMID 23243548, 2012). "Thyroglobulin, calcitonin, and CEA (carcinoembryonic antigen) are tumor markers that can be useful in the management and monitoring of anaplastic thyroid carcinoma (ATC), although their specific utility may vary depending on the patient and other individual disease characteristics." (PMID 39744583, 2025). "Immunohistochemical (IHC) analysis showed that the anaplastic thyroid carcinoma expressed vimentin, while it lacked the expression of CK, CK19, and thyroglobulin." (PMID 41124647, 2026).
schizophrenia (11 papers, 2012 to 2025). A major psychotic disorder characterized by abnormalities in the perception or expression of reality. "The levels of antibody titer represent that thyroid peroxidase-antibody (TPOAb), thyroid-stimulating hormone receptor-antibody (TSHrAb), and thyroglobulin-antibody (TgAb) were raised in the patients suffering from schizophrenia along with thyroid dysfunction." (PMID 33995058, 2021). "It is also possible that hypoalbuminemia, hypotransthyretin and a variety of drugs (androgens, glucocorticoids, growth hormones, and so on) can reduce the thyroglobulin content, producing a false-positive or false-negative outcome in HPTA among patients with schizophrenia." (PMID 32174848, 2020).
thyroid dyshormonogenesis (11 papers, 2014 to 2025). "We present a Qatari patient with an overlooked diagnosis of thyroid dyshormonogenesis due to thyroglobulin gene mutation." (PMID 40453448, 2025). "Genetic analysis via next generation sequencing (NGS) was performed finding two mutations associated with thyroid dyshormonogenesis: c.7813 C > T, homozygous in the exon 45 of the thyroglobulin gene (TG) and c.1682 G > A heterozygous in exon 15 of the SLC26A4 gene (pendrin)." (PMID 34063177, 2021). "Mutations in genes critical for TH biosynthesis, including sodium iodide symporter (NIS; SLC5A5), pendrin (PDS; SLC26A4), thyroglobulin (TG), thyroperoxidase (TPO), thyroid stimulating hormone receptor (TSHR), and dual oxidase 2 (DUOX2), have been causally linked to thyroid dyshormonogenesis." (PMID 38281222, 2024). "Thyroid dyshormonogenesis usually is caused by single gene mutations, encoding globulins involved in TH synthesis (thyroid peroxidase - TPO, thyroglobulin - TG, Na+/I- symporter – SCL5A5/NIS, pendrine – SCL26A4/PDS), or directly influencing TH synthesis and metabolism (DUOX2, DUOX2A, IYD/DEHAL1)." (PMID 35832434, 2022). "Lower circulating total thyroid hormones in SMIM1-/- individuals are not due to reduction in thyroid hormone binding globulin and thyroglobulin levels are not elevated, making thyroid dyshormonogenesis an unlikely cause of their altered thyroid status." (PMID 38906141, 2024).
preeclampsia (10 papers, 2012 to 2025). Preeclampsia is a hypertensive disorder of pregnancy that is characterized by new-onset hypertension with proteinuria presenting after 20 weeks of gestation, and depending on mild or severe forms may initially present with severe headache, visual disturbances, and hyperreflexia. "Specifically, iodine deficiency that is severe enough to lead to hypothyroxinaemia and elevated thyroglobulin was associated with an increased risk of severe preeclampsia/eclampsia in the study population." (PMID 35120491, 2022). "The significantly lower FT3 and FT4 against a background of low UIC among women with preeclampsia, when compared to normotensive women, suggests inadequate iodination of thyroglobulin secondary to iodine deficiency." (PMID 35120491, 2022). "Including three comparison groups of varying severity of preeclampsia in the current study and the concurrent measurement of urinary iodine concentration and serum thyroglobulin has enabled an adequate assessment of the influence of the level of iodine deficiency on the severity of preeclampsia." (PMID 35120491, 2022). "In binary logistic regression models UIC, serum thyroxine and thyroglobulin and were significantly associated with increased odds of preeclampsia-eclampsia syndrome after adjusting for age, gravidity, BMI, TSH, FT3, Hosmer-Lemeshow test chi-square 14.54, p = 0.07)." (PMID 35120491, 2022). "Iodine deficiency, diagnosed in the current study through low UIC, resultant hypothyroxinaemia and elevated thyroglobulin, are independent predictors of preeclampsia." (PMID 35120491, 2022). "This study aimed to investigate thyroid function (TSH, free T3, and free T4)/antibodies (anti-TPO and anti-TG) in patients with preeclampsia." (PMID 26124747, 2015). "In the current study, while anti-TPO antibodies were significantly higher, anti-TG antibodies were significantly lower in women with preeclampsia." (PMID 26124747, 2015). "The Anti-TPO and Anti-TG-level evaluation and their relationship determination with preeclampsia and eclampsia is what make, our study different from other studies that were previously performed in Iran." (PMID 22848832, 2012). "These two studies agree with Federico Mecacci's study result in 2000; that showed a positive relation between Anti-TPO and Anti TG and preeclampsia." (PMID 22848832, 2012). "However, maternal parity was an independent risk factor for gestational hypertension [adjusted OR 0.20 (p-value 0.05) for anti-TPO and 0.20 (p-value 0.04) for anti-TG]." (PMID 33588796, 2021). "In contrast to anti-TG antibodies and TSH, Sudanese patients with preeclampsia had higher levels of T3 and T4 hormones and anti-TPO antibodies irrespective of parity, gestational age, and hemoglobin levels." (PMID 26124747, 2015). "Compared to mothers with both antibodies negative, there was a 73% less chance of gestational hypertension with an unadjusted odds ratio being 0.26 (p-value 0.005) for anti-TPO and 0.27 (p-value 0.011) for anti-TG." (PMID 33588796, 2021).
Stroke (10 papers, 2016 to 2025). Sudden impairment of blood flow to a part of the brain due to occlusion or rupture of an artery to the brain. "Therefore, we retrospectively analyzed our AIS patients with euthyroidism and compared the stroke severity between the two groups with or without elevated thyroid peroxidase antibody (TPO-Ab) and thyroglobulin autoantibody (Tg-Ab) in China." (PMID 35256895, 2022).
vitamin D deficiency (10 papers, 2016 to 2025). A nutritional condition produced by a deficiency of VITAMIN D in the diet, insufficient production of vitamin D in the skin, inadequate absorption of vitamin D from the diet, or abnormal conversion of vitamin D to its bioactive metabolites. "The levels of anti-TPO, anti-TG and the number of patients positive for anti-TPO were significantly higher in the groups with vitamin D deficiency or insufficiency, compared to the group with sufficient vitamin D (p<0.001, p=0.026, p=0.006, respectively)." (PMID 40837651, 2025). "Patients with AT and vitamin D deficiency had a comparable hormonal profile compared to patients with AT and vitamin D sufficiency in terms of TSH (p = 0.39), FT3 (p = 0.30), FT4 (p = 0.31), TG-Ab (0.44) and TPO-Ab (0.35)." (PMID 27571093, 2016).
Hypercholesterolemia (9 papers, 2013 to 2025). An increased concentration of cholesterol in the blood. "GO was confirmed to be associated with smoking, older age, higher TSH receptor antibodies (TRAb) and lower thyroglobulin antibody (TgAb) levels and hypercholesterolemia." (PMID 36554821, 2022).
systemic lupus erythematosus (9 papers, 2014 to 2025). An autoimmune multi-organ disease typically associated with vasculopathy and autoantibody production. "The ratios of lupus-anticoagulants, thyroid peroxidase antibodies, and thyroglobulin antibodies were significantly higher in RSA patients." (PMID 40760512, 2025). "Nine MF patients had positive serology including two with ANA(+), four with positive anti-cardiolipin antibody, two with positive lupus-anticoagulant.and one with positive to thyroglobulin." (PMID 25793623, 2015).
chronic kidney disease (8 papers, 2015 to 2025). Impairment of the renal function secondary to chronic kidney damage persisting for three or more months. "In univariate analysis, Ctn was correlated with gender (p < 0.001), body weight (p = 0.016), height (p = 0.031), body surface area (p = 0.016), thyroid size (p = 0.03), thyroglobulin (p < 0.001), and chronic kidney disease (p < 0.001)." (PMID 38347847, 2024). "In the present study, while we observed lower median urinary iodine concentrations in participants with chronic kidney disease, serum thyroglobulin concentrations were not statistically associated with renal function." (PMID 27455319, 2016).
cyst (8 papers, 2006 to 2025). A sac-like closed membranous structure that may be empty or contain fluid or amorphous material. "Specifically, future research should explore the use of CNB, thyroglobulin measurement in aspirated cyst fluid, and advanced imaging modalities such as diffusion-weighted MRI or FDG-PET to improve preoperative diagnosis." (PMID 40519419, 2025). "Although cyst fluid was rich in thyroglobulin, the presence of anti-thyroglobulin antibodies reduces thyroglobulin levels dramatically." (PMID 34230513, 2021). "Simple serous cysts appear with fluid density on a CT scan, whereas a cyst with haemorrhage or high thyroglobulin content is iso-dense to muscle." (PMID 27271508, 2016). "The patient was diagnosed as having ectopic thyroid tissues because the resected tumor was composed of large follicles and follicular epithelium in the cyst wall that stained positively for thyroglobulin." (PMID 16899136, 2006). "If the FNAC had been repeated and combined with an ultrasound of the thyroid and the central lymphatic compartment, as well as HPV-DNA, TTF-1, or a thyroglobulin analysis on the cyst aspirate, the chances of making a correct initial diagnosis had likely increased." (PMID 39962709, 2025). "Thyroglobulin levels in the case with hypoechoic cyst were higher than normal and the patient underwent thyroid surgery." (PMID 21750638, 2011). "Negative reaction for thyroglobulin was observed in the cyst contents of our case." (PMID 30621638, 2019).
squamous cell carcinoma (8 papers, 2006 to 2025). A carcinoma arising from squamous epithelial cells. "In laboratory tests, some patients had elevated levels of tumor markers (CA199, squamous cell carcinoma antigen level), thyroglobulin levels and tumor-related substances, but all these indicators lacked specificity." (PMID 36052269, 2022). "The squamous carcinoma cells were positive for cytokeratin only but negative for thyroglobulin, TTF1 and calcitonin, confirming the independent origins of the tumors." (PMID 16984659, 2006). "Lack of thyroglobulin positivity in squamous carcinoma cells ruled out the possibility of follicular epithelial origin in our case." (PMID 16984659, 2006).
type 1 diabetes (8 papers, 2017 to 2025). "The present study determined that there is an association between Type-I diabetes mellitus and elevated levels of anti-TPO and anti-TG antibodies in women." (PMID 40735558, 2025). "It is unclear how local autoantigens could contribute to tear autoantibodies to thyroid peroxidase (TPO), a tissue-restricted thyroid secretory protein important in generation of thyroglobulin or IA-2, an islet-specific autoantigen for type 1 diabetes." (PMID 39936155, 2024).
Encephalopathy (7 papers, 2016 to 2024). Encephalopathy is a term that means brain disease, damage, or malfunction. "Complementary investigations showed elevated titres of anti-thyroglobulin and anti-thyroperoxidase antibodies (200 and 10 times, respectively, as compared to normal levels) and electroencephalography were suggestive of encephalopathy." (PMID 26786766, 2016).
endothelial dysfunction (7 papers, 2014 to 2024). In vascular diseases, endothelial dysfunction is a systemic pathological state of the endothelium (the inner lining of blood vessels) and can be broadly defined as an imbalance between vasodilating and vasoconstricting substances produced by (or acting on) the endothelium. "The low UIC and trend towards the elevation of thyroglobulin suggest that inadequate iodine intake may have increased TSH levels and indirectly caused endothelial dysfunction." (PMID 34210226, 2021).